KLK3 (kallikrein related peptidase 3)
Diseases named in the same sentence as KLK3 in open-access papers (continued):
Sharing a sentence is not in itself a finding about the gene and the disease.
prostate carcinoma (continued). "In prostate cancer and some non-malignant conditions, such as benign prostatic hyperplasia and prostatitis, KLK3 is also released into the blood circulation." (PMID 34948344, 2021). "In conclusion, we propose that KLK1, KLK2, KLK3 KLK4, KLK8, KLK9, and KLK14, which are differentially expressed in prostate cancer, could be used as promising biomarkers of prostate cancer progression." (PMID 33150763, 2020). "In order to investigate if 11KT and 11KDHT demonstrate androgenic activity on endogenous AR-regulated genes, the mRNA expression levels of KLK3 (NM_001030047), FKBP5 (NM_001145775) and TMPRSS2 (NM_001135099) were assessed in two androgen dependent prostate cancer cell lines, LNCaP and VCaP." (PMID 27442248, 2016). "Previous research identified four single nucleotide polymorphisms (SNPs) principally associated with circulating PSA levels rather than with prostate cancer risk (TERT rs2736098, FGFR2 rs10788160, TBX3 rs11067228, KLK3 rs17632542)." (PMID 26431041, 2015). "Of note, among the genes repressed by AMPK was KLK2, a prostate cancer marker and a well-established AR target gene that belongs to the same gene family (kallikrein-related peptidases) as prostate specific antigen (PSA / KLK3)." (PMID 25003216, 2014). "As both KLK3 and KLK2 genes are regulated by AR signalling, it is reasonable to theorize that the 11B6 antibody could be used to image AR signalling in prostate cancer in a similar fashion to that reported with 5A10." (PMID 26116115, 2014). "Prostate cancer cells secrete BMP1, IGF, PDGF, vascular endothelial growth factor (VEGF), endothelin 1 (EDN1), plasminogen activator urokinase (PLAU) and kallikrein-related peptidase 3 (KLK3; also known as PSA), which regulate osteoblast proliferation or differentiation." (PMID 31753020, 2019). "The SNPs identified are mainly in regions that had not previously been known to be associated with prostate cancer risk that might be clinically relevant, such as MYC, MSMB, KLK2 and KLK3 genes." (PMID 27819754, 2017). "In order to determine whether N-linked glycosylation alters AR activity, we evaluated the effect of tunicamycin on the expression of Kallikrein 3 (KLK3), which is a direct AR target protein, and also a well-characterized biomarker for prostate cancer and known glycoprotein." (PMID 23724116, 2013). "The MYLK, KLK2, KLK3, HAN11, LTF, CSRP1 and TGM4 genes presented significant changes in their functional connectivity between normal and tumoral conditions and were also classified as the top seven most informative genes for the prostate cancer genesis process by our discriminant analysis." (PMID 19055846, 2008). "This heterogeneity of response of various prostate cancer cells to alterations in KLK3 expression may explain why a lower level of CDH1 in CTCs was only observed in one of four models, despite the consistent decrease in KLK3 across all models, in the present study." (PMID 34206049, 2021). "However, a loss in this protein expression has been reported in undifferentiated prostate carcinomas, which could explain a lack of KLK3 expression in some CTCs sets." (PMID 33635497, 2021). "For PCa patients, prostate cancer cells may be present despite the absence of KLK3 mRNA." (PMID 34771706, 2021). "In addition, AR is a TF regulating KLK3 transcript levels and, interestingly, AR-negative prostate cancer PC3 cell line does not present a promoter annotation for KLK3 gene, hence indicating the absence of ChIP-seq signal supporting the presence of a promoter for KLK3 gene." (PMID 33186463, 2020). "In conclusion, KLK2, KLK3, KLK4, KLK5, KLK11, and possibly KLK15 are important for normal prostate physiology but become reprogrammed in prostate cancer to drive tumor progression." (PMID 41516101, 2025). "In prostate cancer, elevated levels of KLK2, 4 and 13–15 mRNA and/or protein have been reported; KLK3, 5, 7, 10 and 11 are decreased compared to nonmalignant tissue counterparts." (PMID 24294176, 2013).
breast carcinoma (101 papers, 1995 to 2026). "Furthermore, the promoter and enhancer regions of KLK3 have been shown to be mutated in breast cancer." (PMID 36140706, 2022). "In vitro studies have shown that sera obtained during the menstrual cycle can stimulate KLK3 production in a breast cancer cell line (T-Line 47D)." (PMID 34444582, 2021). "For example, 2038 and 2340 intron retention events have been detected in breast cancer and lung carcinoma, respectively, while intron 4 of KLK3 (PSA) transcript was specifically retained in the majority of patients in a prostate cancer cohort." (PMID 30795533, 2019). "KLK3 was previously shown to have an antiangiogenic and a tumour suppressor effect on the growth of some breast cancer cell lines." (PMID 14710225, 2004). "In this article we report for the first time that KLK15, like KLK3, is an independent favourable prognostic marker for breast cancer." (PMID 12439720, 2002). "Herein, GSEA revealed that ARGs might be involved in the process of transcription of genes KLK2 and KLK3 in breast cancer, which might offer clues for a more in-depth investigation of ARGs and anoikis resistance in breast cancer." (PMID 37842046, 2023). "KLK2 and KLK3 are both upregulated by progesterone in breast cancer cell lines." (PMID 34444582, 2021). "As androgen receptor pathway activation has been found to promote a subset of breast cancer, the role of KLK3 involved in tumor progression may need further investigation." (PMID 34650974, 2021). "With respect to breast cancer in particular, several kallikrein family members, namely KLK3, KLK5, KLK6, KLK10, KLK12, KLK13, and KLK14 were shown to be differentially expressed at the mRNA or protein levels within the cancerous tissues or serum of such patients." (PMID 16434994, 2006). "For example, KLK3 (prostate specific antigen, PSA) is used as a blood biomarker for prostate cancer, and alterations of KLK4, KLK5, and KLK6 have been suggested to play a role for breast cancer aggressiveness." (PMID 38961454, 2024). "Using human‐specific primers, we determined mRNA levels of prostate‐specific antigen (PSA) or Kallikrein 3 (KLK3), considered a marker of androgenic activity in prostate and breast cancer cells." (PMID 34042278, 2021). "Like ERRα activity, the mRNA levels of ERRα target genes, KLK3, ENO1 or TAPBPL, were also significantly elevated in GREM1-overexpressing breast cancer cells." (PMID 32572171, 2020). "Treatment with XCT790 significantly reduced the mRNA level of GREM1 as well as that of KLK3, one of the ERRα target genes, in MDA-MB-453 and SKBR3 breast cancer cells." (PMID 32572171, 2020). "Interestingly, the results obtained for KLK14 in this study are comparable to those obtained for KLK3, KLK6 and KLK15 in breast cancer and KLK4, KLK5 and KLK10 in ovarian cancer, in that high expression of these kallikrein genes also correlated with patient prognosis." (PMID 12439719, 2002). "KLK3 and AZGP1 expression were not strongly correlated with AR expression in all breast cancer subtypes." (PMID 34736512, 2021). "Unlike KLK3, RPL32 is also expressed in mice, so a test was performed to confirm there was no detection of mouse cells with these primers and amplification conditions using mouse mammary cell line 4T1 and human breast cancer cell line MDA-MB-231." (PMID 34206049, 2021).
benign prostatic hyperplasia (100 papers, 2008 to 2026). A non-cancerous nodular enlargement of the prostate gland. "Remarkably, the percentage of clipped free KLK3 is highly related to benign prostatic hyperplasia." (PMID 26582203, 2016). "However, increased levels of KLK3 are also observed in some patients with benign prostate hyperplasia." (PMID 19055846, 2008).
prostatitis (73 papers, 2004 to 2026). An infectious or non-infectious inflammatory process affecting the prostate gland. "When ARG2 was compared with KLK3 in the Global-Prostate dataset, we observed that the ARG2 high and KLK3 low quadrant was significantly sparse (FDR < 1e-4), thereby satisfying criteria for a Boolean implication relationship." (PMID 29464091, 2018).
ovarian carcinoma (68 papers, 2002 to 2025). A malignant neoplasm originating from the surface ovarian epithelium. "FBLN1, a calcium-binding, acidic glycoprotein of extracellular matrix, is positively correlated with ovarian cancer progression; and elevated expression of KLK3 and TMPRSS2 have been associated with PCa aggressiveness." (PMID 21134280, 2010). "Intriguingly, glycosylation patterns of KLK3 and KLK6 seem to correlate with prostate and ovarian cancer stages." (PMID 27898009, 2016). "KLK-3 is a screening biomarker and an indicator of disease progression, and it has been studied extensively, while the other enzyme from this family, KLK-6, has been analyzed as a biomarker for ovarian cancer." (PMID 33996745, 2021).
metastatic prostate carcinoma (57 papers, 2005 to 2026). A carcinoma that arises from the prostate gland and has spread to other anatomic sites. "KLK3 is a prognostic marker for progression-free survival in patients with metastatic prostate cancer." (PMID 34209090, 2021).
prostate adenocarcinoma (53 papers, 2008 to 2026). "In descending order of importance for the prostate lineage genes, NKX3-1, KLK3, ACPP, SLC45A3 and FOLH1 were the most important predictors for prostate adenocarcinoma based on the discriminant loading > 0.3." (PMID 33762601, 2021). "In prostate adenocarcinoma (PRAD), the family of KLK genes KLK2, KLK3, and KLK4 are enriched in both the prostate and prostate cancer." (PMID 40453216, 2025).
prostate tumor (52 papers, 2006 to 2025). "Several AR-associated genes (AR, FOLH1, KLK3, NKX3-1, TMPRSS2) showed minimal change in the metastatic dura adenocarcinoma as compared to the primary prostate tumor, while there was a marked downregulation of these AR-related transcripts in the metastatic brain NEPC lesion." (PMID 39349591, 2024). "Accumulated evidence supported that prostate tumor expansion may correlate with epigenetic reorganization in the KLK3 genomic regulatory elements reproduced by alterations of the KLK3 eRNA expression." (PMID 36287118, 2022). "qRT-PCR analysis was conducted on the cells bound to the microchannels to detect mRNAs associated with prostatic tissues, androgen receptor (AR), and prostate-specific antigen (kallikrein-related peptidase 3 or KLK3), as well as prostate tumor-derived genes prostate cancer antigen 3 (PCA3) and PSMA." (PMID 34771706, 2021). "Moreover, among the identified genes we found classically known biomarkers and genes which are closely related to tumoral prostate, such as KLK3 and KLK2 and several other potential ones." (PMID 19055846, 2008). "Of these epithelial cell clusters, two subclusters of LE cells (LE KLK3+ and LE KLK4+) were representative of prostate tumors." (PMID 40723207, 2025). "In contrast, other gene loci that are highly expressed in prostate tumor cells, such as TMPRSS2 and KLK3 showed very different (and expected) methylation patterns in the same dataset, excluding the possibility of an artifact in the WGBS." (PMID 38112617, 2024). "Notably, genes associated with luminal differentiation (i.e. FOXA1, TMPRSS2, HOXB13, KLK3, KLK2) had significantly reduced expression in the ‘low’ NKX3.1 prostate tumors." (PMID 30266798, 2018). "Interestingly, the only evidence, EST (BF372485), in the public database for one of the tumor-specific splice event joining one of the intron in KLK3 gene to an intron in KLK2, is also derived from prostate tumor-tissue." (PMID 23181285, 2012).
lymph node metastasis (34 papers, 2012 to 2026). "In a multivariable Cox regression model, detectable KLK3 mRNA levels and presence of lymph node metastasis were both independent predictors of shorter PFS (HR 5.07; 95% CI 1.81–14.18; P = 0.0020 and HR 2.57; 95% CI 1.20–5.50, P = 0.0149 respectively)." (PMID 33650292, 2021).
pancreatic cancer (25 papers, 2006 to 2025). "Of the 30 Indicator genes studied in pancreatic tissue, only KLK3 was not expressed in pancreatic cancer or chronic pancreatitis samples." (PMID 21245863, 2011).
Pca (13 papers, 2014 to 2025). "Our research has confirm that, patients with the SNP of the KLK3 gene, rs2735839, carrying the allele GG and AG, has a PCa risk 3.7 times higher than that carrying A homozygotes (OR = 3.78, 95% CI = 2.03 ~~ 7.07, P = 0.00)." (PMID 24755043, 2014). "This classifier comprised a panel of five proteins (i.e., FOLH1, KLK3, TGFB1, SPARC, and CAMKK2) that are capable of stratifying PCa patients according to the risk of aggressiveness." (PMID 36551580, 2022). "Studies on the relationship between the KLK3 and VDR polymorphisms as well as environmental factors and PCa occurance are very limited." (PMID 24755043, 2014). "It has been confirm that the single nucleotide polymorphisms (SNPs) rs2735839 of KLK3 and the SNPs rs731236 of VDR are associated with PCa." (PMID 24755043, 2014). "In summary, the results of this study suggest that the occurrence of PCa is related to the genotype of KLK3 SNPs rs2735839." (PMID 24755043, 2014). "The appearing frequencies of AA, AG, and GG genotypes at the SNPs rs2735839 (A/G) for KLK3 were 13.89%, 62.96% and 23.15% in PCa and 37.19%, 44.63%, 18.18% in control, respectively; these two groups are statistically different (P = 0.00)." (PMID 24755043, 2014). "The analysis of environmental risk factors and genetic factors KLK3 gene polymorphisms (SNPs) rs2735839 revealed that multiplied interaction exists between tea consumption and rs2735839; Tea consumption may be against the dangerous gene GG + GA and protect people from PCa." (PMID 24755043, 2014). "This study is focused on the relationship between the KLK3 and VDR gene SNPs as well as environmental risk factors, and the occurance of PCa within the Chinese population." (PMID 24755043, 2014). "In addition to its widespread role in PCa diagnosis, KLK3 is involved in the progression of tumors towards metastasis by supporting cell proliferation and angiogenesis." (PMID 36551580, 2022). "In addition to KLK3, the high-level expressions of CD133 and GRHL2 were observed in PCa and increased during disease progression." (PMID 36551580, 2022). "The SNPs rs2735839 for KLK3 is strongly related to the development of PCa, while the SNPs rs731236 for VDR is not." (PMID 24755043, 2014).
bladder cancer (12 papers, 2015 to 2025). "The PCR signals of six genes (KLK3, TMPRSS2, KLK4, IGF1R, VEGF, and MYC) were successfully amplified in bladder cancer cell lines." (PMID 32781788, 2020).
cervical carcinoma (10 papers, 2010 to 2025). A carcinoma arising from either the exocervical squamous epithelium or the endocervical glandular epithelium. "Notably, the integration of HPV DNA was much more frequent in cervical cancer compared with anal cancer and was associated with a low HPV copy number (<4, ratio of the number of HPV reads over the control human kallikrein-3 (KLK3) gene) and worse progression-free survival." (PMID 34830902, 2021).
breast tumours (8 papers, 1995 to 2022). "Prostate specific antigen (PSA), also known as kallikrein-3 (KLK3), first identified in seminal plasma and prostatic tissue, produced by the epithelial cells lining the acini and ducts of prostate gland, has also been identified in female breast tumours." (PMID 29344009, 2018).
testicular cancer (7 papers, 2012 to 2024). A primary or metastatic malignant neoplasm that affects the testis. "Among them, 3 genes were approved by FDA for cancer diagnosis, including: EGFR, KLK3 (PSA) and AFP for the diagnosis of colon, prostate and testis cancers, respectively." (PMID 22761861, 2012).
male infertility (6 papers, 2013 to 2023). The inability of the male to effect fertilization of an ovum after a specified period of unprotected intercourse. "If KLK3 is the key executor of semen liquefaction process, a loss of KLK3 production due to surgical removal of prostate glands (prostatectomy) would result in a liquefaction defect and ultimately male infertility." (PMID 32529252, 2020). "Of 28 KLK3 substitutions, 5 SNPs (rs266881, rs174776, rs1810020, rs266875, and rs35192866) appear to be strong risk factors for male infertility, while 1 SNP (c.206 + 235 T > C) is protective." (PMID 32529252, 2020). "This is the first study reporting the association of KLK3 SNPs with male infertility; however, the functional significance of these polymorphisms remains to be worked out." (PMID 28894123, 2017).
thyroid cancer (6 papers, 2015 to 2025). "Additionally, KLK3 (human denotation of KLK1 in mouse) is among the involved molecules in all groups that show an impact on thyroid cancer signalling." (PMID 26492889, 2015).
renal cell carcinoma (5 papers, 2014 to 2024). "In terms of renal cell carcinoma (RCC), clinical experimental studies have proven that some KLKs, such as KLK1, KLK3, KLK6, KLK7, and KLK15, are differentially expressed in different subtypes of RCC, and KLK6 has predictive value in RCC." (PMID 39116105, 2024).
kidney cancer (4 papers, 2015 to 2024). Primary or metastatic malignant neoplasm involving the kidney. "We found that LSD1 binds to AR target genes including KLK2, KLK3, and TMPRSS2 in kidney cancer cells, and confirmed that the binding decreased in LSD1 shRNA-expressing cells." (PMID 32847068, 2020).
head and neck squamous cell carcinoma (2 papers, 2018 to 2023). A squamous cell carcinoma that arises from any of the following anatomic sites: lip and oral cavity, nasal cavity, paranasal sinuses, pharynx, larynx, and salivary glands. "Five KLKs were commonly downregulated in head-neck squamous cell carcinoma and breast invasive carcinoma: KLK3 (3-fold and 4-fold), KLK6 (2-fold and 6-fold), KLK7 (2-fold and 10-fold), KLK11 (5-fold and 6-fold) and KLK13 (8-fold and 3-fold)." (PMID 29707153, 2018).
Hirsutism (2 papers, 1997 to 2021). Abnormally increased hair growth referring to a male pattern of body hair (androgenic hair). "In addition, Ferriman–Gallwey score, which is used to evaluate hirsutism, was compared with KLK3." (PMID 34444582, 2021). "Recent studies have reported the presence of KLK3 in female serum in relation to polycystic ovary syndrome (PCOS) and hirsutism." (PMID 34444582, 2021).
Infertility (2 papers, 2017 to 2023). "In order to understand the contribution of KLK3 genetic variations to infertility risk, we re-sequenced its complete coding region in 875 infertile and 290 fertile men." (PMID 28894123, 2017). "Our findings suggest that polymorphisms in the KLK3 gene correlate with infertility risk." (PMID 28894123, 2017). "We analyzed the complete coding region of the KLK3 gene in ethnically matched 875 infertile and 290 fertile men to find if genetic variations in KLK3 correlate with infertility." (PMID 28894123, 2017). "Therefore, KLK3 analysis in infertile individuals from ethnically different populations is strongly recommended." (PMID 28894123, 2017).
leukaemia (2 papers, 2017 to 2022). "This difference is mainly found in proteins functionally related to each pathology, for example: sCD44, HIF1A, ZMYM3 or PTPRC for CSF + LM in lymphoma and S100A9, TRAF3, KLK3, KLK2, PTPRC, among others, in the case of CSF + LM in leukemia." (PMID 35053611, 2022).